OPRM1 (opioid receptor mu 1)
Diseases named in the same sentence as OPRM1 in open-access papers (continued):
Sharing a sentence is not in itself a finding about the gene and the disease.
psoriasis (4 papers, 2019 to 2024). An autoimmune condition characterized by red, well-delineated plaques with silvery scales that are usually on the extensor surfaces and scalp. "We found that the frequency of the genetic variant rs1229984 (ADH1B) increased in the whole psoriasis group, while genetic variant rs1799971 (OPRM1) showed higher prevalence in the familial form of psoriasis patients." (PMID 31011876, 2019). "Furthermore, the G allele of the rs1799971 (OPRM1) was also significantly associated with increased psoriasis risk in the additive and dominant models (ORadditive = 1.75, 95% CI 1.27–2.43, p = 0.001, ORdominant = 1.82, 95% CI 1.26–2.63, p = 0.001)." (PMID 31011876, 2019). "While effect allele ‘G’ of rs1799971 (OPRM1) also associated with increased risk of early onset and familial aggregation of psoriasis in the additive and dominant models (ORadditive = 1.75, 95% CI 1.27–2.43, p = 0.001, ORdominant = 1.82, 95% CI 1.26–2.63, p = 0.001)." (PMID 31011876, 2019). "Importantly, OPRM1 is also involved in itch, a sensation reported by 70–90% of patients with psoriasis, calling for further studies to assess the psoriasis–itch–disease associated stress–alcohol consumption circle both at the level of clinical as well as of genetic studies." (PMID 34067223, 2021). "By stratifying the psoriasis group, significant results were also found in the case of rs1799971 (OPRM1) when familial cases were compared to sporadic cases." (PMID 34067223, 2021). "recognized estrogen receptor 1 (ESR1), opioid receptor mu 1 (OPRM1), and hydroxysteroid 11-beta dehydrogenase 1 (HSD11B1) as promising therapeutic targets for psoriasis." (PMID 39883516, 2024).
substance abuse (4 papers, 2020 to 2023). The use of a drug for a reason other than which it was intended or in a manner or in quantities other than directed. "Some of us previously investigated involvement of eight genes in the opioid system (OPRD1, OPRK1, OPRL1, OPRM1, PDYN, PENK, PNOC, and POMC) and their potential effects on substance abuse." (PMID 34440333, 2021).
anxiety disorder (3 papers, 2006 to 2025). A category of psychiatric disorders which are characterized by anxious feelings or fear often accompanied by physical symptoms associated with anxiety. "Slc1a3, encoding a GABA transporter, has also been formally associated to be more expressed in males with Manic Depressive Disorder and is considered a candidate gene for targeting anxiety disorders, was also activated in Oprm1-positive striatal cells following morphine withdrawal." (PMID 36534642, 2022).
Cognitive impairment (3 papers, 2018 to 2025). Abnormal cognition is characterized by deficits in thinking, reasoning, or remembering. "Therefore, it was hypothesized that AA patients for OPRM1, exhibiting a greater activation of the mu-receptor, would have cognitive deficits as described with the activation of the κOR, explaining their lower cognitive performance and the subsequent impact on their quality of life." (PMID 36123640, 2022). "However, the conclusion is that interactions between EPHB2, OPRM1, and PER2 lead to cognitive impairment, which is not sufficiently supported by the observed changes in expression levels." (PMID 39002057, 2025).
glioblastoma (3 papers, 2020 to 2024). The most malignant astrocytic tumor (WHO grade IV). "In contrast to OPRM1 mRNA, GalR1 mRNA encoding for the galanin receptor 1 is abundant in most glioblastoma specimens (second box plot)." (PMID 32560384, 2020). "In glioblastoma cells, d,l-methadone, an opioid receptor agonist, stimulates OPRM1 and instigates inhibitory Gi proteins, which inhibit adenylyl cyclase activity, lowering [cAMP]i." (PMID 38802344, 2024). "It has been reported that prolonged exposure of leukemia and glioblastoma cells to doxorubicin lead to an increased expression levels of OPRM1 on these cells." (PMID 35182225, 2022). "Querying the glioblastoma database of The Cancer Genome Atlas (TCGA) for the mRNA abundances of putative methadone targets indicates undetectably low OPRM1 (μ-opioid receptor) mRNA abundance in the majority of glioblastoma specimens (first box plot)." (PMID 32560384, 2020). "To test for tumoricidal effects of methadone in glioblastoma, we first analyzed expression of the μ-opioid receptor (OPRM1) and the NMDA receptor subunit ζ1 (GRIN1) in our human glioblastoma cell lines A172, T98G and U251 by RT-PCR and in part, by western blotting." (PMID 32560384, 2020). "OPRM1- and GRIN1-specific mRNA could be detected in all three glioblastoma lines." (PMID 32560384, 2020).
insomnia (3 papers, 2015 to 2023). A sleep disorder characterized by difficulty in falling asleep and/or remaining asleep. "In a separate study, 18% of patients on methadone maintenance therapy (MMT) were categorized as having insomnia (those that had higher doses of methadone had increased severity of insomnia), and 12 OPRM1 SNPs were significantly associated with increased insomnia scores." (PMID 36869037, 2023). "More recently, the insomnia side-effect was found to be associated with genetic variations in the μ-opioid receptor (OPRM1) gene, which indicates that susceptible polymorphisms may also affect sleep control among patients on methadone." (PMID 25870765, 2015).
neonatal abstinence syndrome (3 papers, 2017 to 2025). A constellation of neurobehavioral features observed in a neonate following antenatal exposure to drugs including opioids, benzodiazepines, and selective serotonin reuptake inhibitors. "For instance, morphine treatment of neonatal abstinence syndrome (NAS) is associated with decreased DNA methylation at 1 of 4 CpG sites within the OPRM1 gene." (PMID 40230379, 2025). "Furthermore, following opioid exposure, hypermethylation within the OPRM1 promoter is repeatedly observed in infant’s cord blood or saliva with neonatal abstinence syndrome, suggesting the likelihood of OPRM1 gene suppression in the offspring." (PMID 36233105, 2022). "Increased OPRM1 promoter methylation may lead to gene silencing and worsen the outcomes of neonatal abstinence syndrome." (PMID 28253273, 2017).
Parkinson disease (3 papers, 2020 to 2024). A progressive degenerative disorder of the central nervous system characterized by loss of dopamine producing neurons in the substantia nigra and the presence of Lewy bodies in the substantia nigra and locus coeruleus. "Furthermore, frequent variants of OPRM1 have been correlated with impulse control disorders in Parkinson patients recently." (PMID 39318779, 2024).
periodontitis (3 papers, 2019 to 2024). An acute or chronic inflammatory process that affects the tissues that surround and support the teeth. "Our results consistently showed that the individuals used for comparison (light smokers, ex-smokers, non-smokers, or a combination of them) tended to have more often dental caries and periodontitis in the presence of OPRM1 genetic variation." (PMID 30973902, 2019). "When mental illness and dental clinical data (tooth loss, dental caries, and periodontitis) were used as covariates, there were associations between heavy smoking and OPRM1, when non-smokers were used as comparison." (PMID 30973902, 2019).
rheumatoid arthritis (3 papers, 2017 to 2023). A chronic, systemic autoimmune disorder characterized by inflammation in the synovial membranes and articular surfaces. "Finally, several genes (SEMA7A, CSK, GUCY1A2, EMCN, OPRM1) are associated with rheumatoid arthritis (RA)." (PMID 36658473, 2023).
asthma (2 papers, 2022 to 2025). "Our results demonstrated an association between the rs1799971 in OPRM1 and asthma." (PMID 36395102, 2022). "They found that patients with asthma carrying the OPRM1 GG genotype exhibited enhanced airway hyperresponsiveness, attributable to enhanced Th2 cell differentiation in the regional lymph node." (PMID 36395102, 2022).
breast tumor (2 papers, 2017 to 2021). "Correlation between clinicopathological characteristics and OPRM1 methylation in breast tumor tissue DNA and peripheral blood leukocyte DNA." (PMID 35024367, 2021). "We also investigated the effects of environmental factors on OPRM1 methylation in breast tumor DNA and the relationship between OPRM1 methylation and clinicopathological features in tumor DNA and PBL DNA." (PMID 35024367, 2021).
Dysmenorrhea (2 papers, 2017 to 2018). Pain during menstruation that interferes with daily activities. "The endogenous system of opioid receptors (OPRM1 and OPRD1) is well known for its analgesic potential; XGDP may treat dysmenorrhea through regulating central analgesic effects." (PMID 29234428, 2017).
glaucoma (2 papers, 2023 to 2024). Increased pressure in the eyeball due to obstruction of the outflow of aqueous humor. "Oprm1 overexpression in RGCs significantly improved visual perception in a high intraocular pressure-induced glaucoma model, implying its future translational potential." (PMID 38467611, 2024). "AAV2-mediated specific overexpression of Oprm1 in RGCs enhanced cell survival in glaucoma model at eight weeks after IOP elevation." (PMID 38467611, 2024). "We used two visual-based behavioral assays to assess how visual functions in the glaucoma model were affected by Oprm1 overexpression at eight weeks following microbeads injection." (PMID 38467611, 2024). "Finally, we investigated whether overexpression of Oprm1 in RGCs could protect neurons from an experimental model of high intraocular pressure-induced glaucoma." (PMID 38467611, 2024). "Although Oprm1 is preferentially expressed in intrinsically photosensitive retinal ganglion cells (ipRGCs), its neuroprotective effect could be transferred to multiple RGC subclasses by specific overexpressing Oprm1 in pan-RGCs in ONC, excitotoxicity, and glaucoma models." (PMID 37645816, 2023).
melanoma (2 papers, 2019 to 2020). A malignant, usually aggressive tumor composed of atypical, neoplastic melanocytes. "However, cell lines expressing OPRM1 were rather rare in this biobank of melanoma cells." (PMID 35601274, 2019). "Various doses of methadone did not affect cell viability of melanoma cell lines grouped into μ‐opioid receptor density (OPRM1 high, medium, negative)." (PMID 32306524, 2020).
mental disorder (2 papers, 2019 to 2025). A disease that has its basis in the disruption of mental process. "However, current research on SLC6A3 predominantly relates to mental disorders, while studies on OPRM1 primarily focus on pain management." (PMID 40910010, 2025).
oral cancer (2 papers, 2018 to 2023). "Viral- and nonviral-mediated delivery of genes for the μ-opioid receptor and the endothelin B receptor (OPRM1 and EDNRB, respectively) produce endogenous analgesia through the secretion of opioids by the carcinoma in preclinical oral cancer pain models." (PMID 30405367, 2018).
psychosis (2 papers, 2019 to 2020). "Genetic variation in the human Oprm1 gene has been associated with MA dependence/psychosis, but additional research results in this area have not appeared in the literature." (PMID 31274109, 2019). "Previous findings indicate that Oprm1 regulation and opioid system activity contribute to MA consumption in mice, and MA dependence/psychosis in humans." (PMID 31274109, 2019).
Sciatica (2 papers, 2018 to 2020). Pain in the lower back and hip radiating in the distribution of the sciatic nerve. "The risk for persistent CLBP and sciatica is increased by the SNPs A118G, rs1799971, in the opioid receptor μ 1 (OPRM1) gene." (PMID 29890676, 2018).
alcohol addiction (1 paper, 2022). "These behavioral alterations were accompanied by significant changes in the gene expression of critical targets underlying alcohol addiction, such as the mu-opioid receptor (Oprm1), reduced in the NAcc of naïve CB2KO mice." (PMID 35682586, 2022).
brain tumor (1 paper, 2018). "In the S037 dataset issued from microglia collected from a brain tumor, OPRM1 was highly expressed." (PMID 30662412, 2018).
dental caries (1 paper, 2019). The decay of a tooth, in which it becomes softened, discolored, and/or porous. "Dental caries in the presence of OPRM1 genetic variation was less likely to occur for comparisons 7—Heavy Smokers, Light Smokers and Ex-Smokers versus Non-Smokers and 10—Ex-Smokers versus Non-Smokers, and more likely for comparison 9—Light Smokers versus Ex-Smokers." (PMID 30973902, 2019).
embryonal carcinoma (1 paper, 2022). A non-seminomatous malignant germ cell tumor characterized by the presence of large germ cells with abundant cytoplasm resembling epithelial cells, geographic necrosis, high mitotic activity, and pseudoglandular and pseudopapillary structures formation. "For instance, the Oprm1 gene is completely suppressed in mouse embryonal carcinoma P19 cells; however, there is a robust increase in Oprm1 expression when the cells are differentiated by retinoic acid." (PMID 36233105, 2022).
Headache (1 paper, 2021). Cephalgia, or pain sensed in various parts of the head, not confined to the area of distribution of any nerve. "SNPs in pharmacodynamic targets have been to a lesser extent linked with side drug adverse effects in headaches, but examples of such variants can be found in the COX 1 gene (PTGS1; aspirin) or in OPRM1 (opioids) or in voltage-gated calcium channels (verapamil)." (PMID 35222013, 2021).
ischemic stroke (1 paper, 2021). A stroke disorder caused by obstruction of blood flow to the brain, due to thrombotic (local blood clot formation) or embolic (due to a blood clot or other material traveling from another site) event. "Taken together, OPRM1 and ADORA1 may be associated with the susceptibility of ischemic stroke through the inflammatory pathway." (PMID 34483854, 2021). "In conclusion, LPAR3, ADORA1, GPR17, and OPRM1 may serve as therapeutic targets of ischemic stroke." (PMID 34483854, 2021). "LPAR3, ADORA1, GPR17, and OPRM1 may serve as therapeutic targets of ischemic stroke." (PMID 34483854, 2021).
non-alcoholic steatohepatitis (1 paper, 2014). "Genes encoding IL1R1 (1.99, p<0.04), OPRM1 (2.65, p<0.02), SIGMARI (3.13, p<0.03), THRB (1.94, p<0.02) and ZFP91 (3.09, p<0.01) mRNA were upregulated in the gastric tissue of patients with non-alcoholic steatohepatitis (NASH) compared to those without NASH." (PMID 25289139, 2014).
rectal adenocarcinoma (1 paper, 2024). "However, upon further differential gene expression comparative analysis, it was noted that although all genes except OPRM1 and ADRA1A showed expression in colon and rectal adenocarcinoma, their levels of expression were not as high as CTSB and CPNE1, which demonstrated the maximum expression." (PMID 38544823, 2024).
scoliosis (1 paper, 2023). A congenital or acquired spinal deformity characterized by lateral curvature of the spine. "This study aimed to determine connection between OPRM1 and rs1205 CRP SNPs in pediatric patients postoperatively and pain intensity, the opioid dose needed to control pain after scoliosis correction, and other clinical aspects." (PMID 38137077, 2023). "The aim of this article is to investigate whether the OPRM1 A118G and rs1205 CRP SNPs influence the perception of pain and the need for opioid analgesics immediately after orthopedic correction of scoliosis in a group of patients under 18 years of age." (PMID 38137077, 2023).
Somnolence (1 paper, 2023). "Somnolence was detected more frequently in HTR2A rs6314 C/C (wild type) and OPRM1 rs1799971 A/A subjects vs. C/T or G carriers." (PMID 36873203, 2023).
type 2 diabetes mellitus (1 paper, 2018). A type of diabetes mellitus that is characterized by insulin resistance or desensitization and increased blood glucose levels. "Examples of predicted applicable diseases of sinomenine are adiposity and type II diabetes mellitus, implying that sinomenine is effective for treatment of adiposity and type II diabetes mellitus based on the target proteins: GAA, OPRM1, OPRD1, OPRK1." (PMID 30046160, 2018).
uterine cancer (1 paper, 2024). Primary or metastatic malignant neoplasm involving the uterine corpus and/or the cervix. "Surprisingly, OPRM1 was downregulated in colorectal and most other cancers, but completely expressed in uterine cancers." (PMID 38544823, 2024).